LINC01680 (long independently transcribed non-coding RNA 1680)
Gene: Long non-coding RNA gene on chromosome 1 (191,221,159 to 191,230,175, reverse strand). Ensembl gene ENSG00000233882.
Diseases named in the same sentence as LINC01680 in open-access papers:
LINC01680 is named in the same sentence as 1 disease in open-access papers, as found by Europe PMC text mining. Sharing a sentence is not in itself a finding about the gene and the disease.
LINC01680 shares sentences with these, for which no sentence is quoted: schizophrenia (1 paper).